RNF4 (ring finger protein 4)
Description:
E3 ubiquitin-protein ligase which binds polysumoylated chains covalently attached to proteins and mediates 'Lys-6'-, 'Lys-11'-, 'Lys-48'- and 'Lys-63'-linked polyubiquitination of those substrates and their subsequent targeting to the proteasome for degradation. Regulates the degradation of several proteins including PML and the transcriptional activator PEA3. Involved in chromosome alignment and spindle assembly, it regulates the kinetochore CENPH-CENPI-CENPK complex by targeting polysumoylated CENPI to proteasomal degradation. Regulates the cellular responses to hypoxia and heat shock through degradation of respectively EPAS1 and PARP1. Alternatively, it may also bind DNA/nucleosomes and have a more direct role in the regulation of transcription for instance enhancing basal transcription and steroid receptor-mediated transcriptional activation. Catalyzes ubiquitination of sumoylated PARP1 in response to PARP1 trapping to chromatin, leading to PARP1 removal from chromatin by VCP/p97.
Synonyms: SNURF; RES4-26; SLX5
Tractability: PROTAC: UniProt records ubiquitination sites on it; ubiquitination databases record sites on it; a small molecule that binds it is known.
Target class: Enzyme; Transferase
Gene: Protein-coding gene on chromosome 4 (2,462,220 to 2,515,859, forward strand). Ensembl gene ENSG00000063978.
Subcellular location: Cytoplasm; Nucleus; Nucleus, PML body
Subcellular location (Human Protein Atlas): Nuclear bodies; Nucleoplasm; Microtubule ends
Pathways (Reactome):
DNA Repair: Processing of DNA double-strand break ends
Immune System: Antigen processing: Ubiquitination & Proteasome degradation
Gene Ontology:
Molecular function: identical protein binding; protein binding; SUMO polymer binding; ubiquitin protein ligase activity; DNA binding; nucleosome binding; ubiquitin-protein transferase activity; zinc ion binding
Biological process: negative regulation of protein localization to chromatin; positive regulation of transcription by RNA polymerase II; proteasome-mediated ubiquitin-dependent protein catabolic process; regulation of kinetochore assembly; regulation of spindle assembly; response to arsenic-containing substance; positive regulation of DNA-templated transcription; protein autoubiquitination; protein K11-linked ubiquitination; protein K48-linked ubiquitination; protein K6-linked ubiquitination; protein K63-linked ubiquitination; protein ubiquitination
Cellular component: cytoplasm; nuclear body; nucleoplasm; nucleus; PML body
Genetic constraint (gnomAD): Loss-of-function variants: 7 observed, 22.52 expected, observed/expected ratio (o/e) 0.31, 90% interval 0.18 to 0.58. The upper end of that interval is the gene's LOEUF score, 0.58, which puts it in group 2 of 6, group 1 being the genes least tolerant of losing a copy. Missense variants: 202 observed, 250.92 expected, observed/expected ratio (o/e) 0.81, 90% interval 0.72 to 0.9. Synonymous variants: 81 observed, 82.32 expected, observed/expected ratio (o/e) 0.98, 90% interval 0.82 to 1.18.
Homologues: Orthologues: chimpanzee RNF4 (100% identical), macaque RNF4 (99% identical), pig RNF4 (94% identical), dog RNF4 (94% identical), mouse Rnf4 (88% identical), rat Rnf4 (88% identical), guinea pig RNF4 (85% identical), tropical clawed frog rnf4 (57% identical), zebrafish rnf4 (45% identical).
Diseases named in the same sentence as RNF4 in open-access papers:
RNF4 is named in the same sentence as 49 diseases in open-access papers, as found by Europe PMC text mining. Sharing a sentence is not in itself a finding about the gene and the disease. The quoted sentences say what the papers report.
promyelocytic leukemia (9 papers, 2013 to 2026). "Meanwhile, RNF4 acts as a tumor suppressor in promyelocytic leukemia (PML) through the degradation of an oncogenic fusion protein between PML protein and retinoic acid receptor α." (PMID 34071450, 2021). "RING finger protein 4 (Rnf4) mediates polyubiquitylation of polysumoylated Nrf2, leading to its subsequent degradation in promyelocytic leukemia-nuclear bodies." (PMID 30890934, 2019). "RNF4 localizes to PML (promyelocytic leukaemia)-NBs (nuclear bodies), and we and others have identified the PML protein and the oncogenic PML-RARα (retinoic acid receptor α) fusion protein as its substrates." (PMID 24151981, 2014). "RNF4 (RING finger protein 4) is a STUbL [SUMO (small ubiquitin-related modifier)-targeted ubiquitin ligase] controlling PML (promyelocytic leukaemia) nuclear bodies, DNA double strand break repair and other nuclear functions." (PMID 24151981, 2014). "A tumor-suppressive role for RNF4 was discovered in acute promyelocytic leukemia (APL), in which the oncogenic driver is a fusion protein that combines the promyelocytic leukemia protein (PML) with RARα (PML-RARα)." (PMID 34572023, 2021). "The ability to chemically synthesize RNF4 will enable future studies of its structure and biological function, particularly its role in degrading the oncoprotein PML-RARα in acute promyelocytic leukemia." (PMID 41636446, 2026). "For example, RNF4 has tumor suppressive activity in acute promyelocytic leukemia (APL)." (PMID 36153321, 2022). "The RING-containing SUMO (small ubiquitin-related modifier)-targeted ubiquitin E3 ligase RNF4 (RING finger protein 4) is responsible for the arsenic-induced ubiquitylation and degradation of the PML (promyelocytic leukaemia) protein." (PMID 23560854, 2013).
melanoma (6 papers, 2021 to 2024). A malignant, usually aggressive tumor composed of atypical, neoplastic melanocytes. "The inability of RNF4-deficient PLX4032-resistant melanoma cells to form colonies was restored upon co-expression of eIF2α a function that is dependent on eIF2α phosphorylation." (PMID 34572023, 2021). "RNF4 is a SUMO-dependent E3 ubiquitin ligase implicated in cancer that regulates the tumorigenesis of melanoma." (PMID 33800394, 2021). "In both melanoma and luminal type-A breast cancer, high levels of RNF4 are associated with poorer prognosis." (PMID 34572023, 2021). "In epithelial cancers, melanoma, and osteosarcoma, RNF4 has a pro-tumorigenic function, which is directly linked to its protein-stabilizing activity." (PMID 34572023, 2021). "Taken together, our data suggest that RNF4 and its downstream target genes, BMP6 and RGMb, are essential for the survival of osteosarcoma and RTKi-resistant melanoma cells and that RNF4 and BMP6 may serve as markers associated with poorer prognosis in sarcomas." (PMID 36153321, 2022). "Breast cancer and melanoma patients exhibiting high levels of RNF4 proteins have poorer prognoses and exhibit resistance to combined RTKi therapy." (PMID 36153321, 2022). "In contrast, RNF4 promotes both in vitro and in vivo tumorigenesis of epithelial cancers and confers resistance to receptor tyrosine kinase inhibitors (RTKi) in melanoma." (PMID 36153321, 2022). "For example, expression of RNF4 confers resistance to PLX4032 in human melanoma cells, and its conditional elimination from PLX4032-resistant tumors in vivo resulted in collapse of the tumors." (PMID 34572023, 2021). "In melanoma patient-derived biopsies, the levels of p-eIF2α correlate with high levels of RNF4 protein." (PMID 34572023, 2021). "The same team recently reported that RNF4 promotes tumorigenesis and confers resistance to targeted therapies in melanoma." (PMID 33800394, 2021). "Along this line, we found that eIF2α is critical for the resistance to therapy induced by RNF4 in melanoma." (PMID 34572023, 2021). "In melanoma, high levels of RNF4 are correlated with high levels of p-eIF2α and are in correlation with unresponsiveness to RTK therapy." (PMID 34572023, 2021). "RNF4 promotes tumorigenesis and therapeutic resistance in melanoma cells, xenograft mouse models, and patient-derived cancer samples." (PMID 34065507, 2021). "High levels of RNF4 are observed in about 40% of melanoma patients and in 30% of colon cancer biopsies." (PMID 34572023, 2021). "In melanoma, the stabilizing activity of RNF4 is not limited to oncogenic transcription factors but also requires the translation initiation factor eIF2α." (PMID 34572023, 2021). "Consistently, patient-derived melanomas display elevated RNF4 and corresponding phosphorylated eIF2α levels, which correlate with poor prognosis and resistance to mitogen-activated protein kinase (MAPK) inhibitors." (PMID 34065507, 2021). "Moreover, the RNF4~BMP6~RGMBP axis is critical for the survival of aggressive bone cancers and melanoma and is associated with poor prognosis of sarcoma patients." (PMID 36153321, 2022). "In epithelial cancers and in melanoma, however, RNF4 has a pro-tumorigenic activity." (PMID 36153321, 2022). "Moreover, the author showed that the RNF4–eIF2α axis plays an important role in the resistance of melanoma cells toward BRAFi." (PMID 33800394, 2021). "However and in cancer, these regulators enhance cancer stem cells tumorigenesis, induce epithelial-mesenchymal transition (EMT) and promote metastasis, including in melanoma Likewise, RNF4 is required for Drosophila and mouse development, yet it has multiple roles in cancer." (PMID 36153321, 2022). "Among them, six E3 ligases were highly expressed in melanoma cells: BRCA1, CUL3, RNF4, UBR5, CHIP, and von Hippel‒Lindau (VHL)." (PMID 39399646, 2024).
melanoma (continued). "The data showed that in melanoma cells with stable knockdown of BRCA1, CUL3, RNF4, UBR5, and CHIP, the reduction in CIP2A levels upon PF treatment was not reversed." (PMID 39399646, 2024). "Here, we report that RNF4 via BMP6 and RGMb is required for tumor cell survival and tumorigenicity of osteosarcoma and RTK inhibitor-resistant melanoma cells (A375R)." (PMID 36153321, 2022). "Moreover, we found that the RNF4-RGMb-BMP6 axis is essential for survival and tumorigenicity of osteosarcoma and therapy-resistant melanoma cells." (PMID 36153321, 2022). "eIF2α was identified as an upstream positive regulator of RNF4-dependent gene signature (but not of the RNF4 gene itself) in human melanoma xenograft tumors conditionally expressing RNF4." (PMID 34572023, 2021).
breast carcinoma (5 papers, 2016 to 2022). "RNF4 knockdown leads to substantial cell death in MDA-MB-231 breast cancer cells and prevents colony formation in soft agar." (PMID 34065507, 2021). "Expression of RNF4 in less aggressive colon and breast cancer cells (SW480 and MCF10, respectively) promotes tumor cell properties such as colony formation in soft agar." (PMID 29615551, 2018). "Furthermore, high RNF4 messenger RNA and protein levels are found in luminal A malignant breast tumors and adenocarcinomas of the colon, respectively, and correlate with a decrease in overall survival." (PMID 34065507, 2021). "Moreover, genetic ablation of RNF4 in aggressive breast cancer cells leads to their rapid death." (PMID 29615551, 2018). "Upon inhibition of miR-7641 expression, the expressions of several of the target genes (RPS16, RNF4, EMC8, and MSRB3) increased, CUL3 expression decreased, and other genes, including PIGC, remained unchanged in MCF-7 breast cancer cells." (PMID 28827731, 2017). "To explore this possibility, we first overexpressed RNF168 and two other DDR-related E3-ligases, RNF4 and RNF8, in the MCF-7 breast carcinoma cells, and studied their effects on FOXM1 expression." (PMID 27526106, 2016).
lung carcinoma (5 papers, 2016 to 2023). "E2 increases RNF4 expression to repress Sp1 levels in premenopausal women with lung cancer, thus decreasing the expression of several miRNAs that can target CD44 and ultimately leading to cancer malignancy." (PMID 35034634, 2022). "Sumoylation of Sp1 at Lys16 increases the recruitment of RNF4, the Sp1 E3-ligase, resulting in the induction of Sp1 degradation at the late stages of lung cancer progression." (PMID 28831131, 2017). "Each unit increase in the relative expression of the EIF2S3, POLDIP2, and RNF4 genes showed protective effects, with odds of having lung cancer decreased by 78%, 84%, and 78%, respectively." (PMID 27418131, 2016). "In summary, our data reveal an unexpected regulatory mechanism in which SUMOylation increases the ability of NDRG2 to inhibit lung cancer tumorigenesis, and RNF4 targets NDRG2 to proteasomal degradation by stimulating its SUMOylation." (PMID 27072586, 2016). "For every unit increase in the relative expression of STAT2 and RNF4 genes, the odds of having lung cancer dropped by 74% and 84%, respectively." (PMID 27418131, 2016). "Therefore, miR-92a-3p enhanced the radiosensitivity of lung cancer cells, and its radiation targets RNF4, MAP3K20, and NIPBL were identified." (PMID 37569824, 2023). "In addition, five of the genes that we identified in this study, CPEB4, DUSP6, NF1, RNF4, and STAT2, were previously proposed as prognostic markers for NSCLC, whereas changes in the expression of MCM4 and WEE1 were associated with lung cancer development." (PMID 27418131, 2016). "miR-18a-5p showed radiosensitive effects on lung cancer cells and suppressed lung tumor growth, and its radiation targets ATM, RNF4, and CCND2 were identified." (PMID 37569824, 2023). "In this report, we present evidence that NDRG2 is also modified by SUMOylation catalyzed by RING finger protein 4 (RNF4) and that SUMOylation is required for NDRG2 regulated tumorigenesis in lung carcinoma cells." (PMID 27072586, 2016). "Our data illustrate a new approach to correlating the expression patterns of NDRG2, RNF4 and SUMO machinery in lung cancer." (PMID 27072586, 2016). "Investigation of the molecular mechanism showed that E2 increases RNF4 expression to reduce Sp1 levels, thereby enhancing CD44 expression through downregulation of several miRNAs, and this leads to a poor prognosis in young women with lung cancer." (PMID 35034634, 2022). "In this study, we found that E2 increased RNF4 to reduce the Sp1 level, thereby enhancing CD44 expression through downregulation of miRNAs, leading to a poor prognosis in young women with lung cancer; this finding may be beneficial for developing therapeutic strategies in the future." (PMID 35034634, 2022).
colon cancer (3 papers, 2018 to 2021). "Analysis of colon cancer biopsies suggests that an elevated level of RNF4 protein is observed specifically at the transition from adenoma to carcinoma." (PMID 34572023, 2021). "In patient-derived colon cancer biopsies, RNF4 was also localizes in the vicinity of the secretory pathway." (PMID 29615551, 2018). "Interestingly, overexpression of RNF4 is observed in lung, breast, and colon cancer cells." (PMID 34065507, 2021).
Fanconi anemia (3 papers, 2023 to 2024). Fanconi anemia (FA) is a hereditary DNA repair disorder characterized by progressive pancytopenia with bone marrow failure, variable congenital malformations and predisposition to develop hematological or solid tumors. "Factors that normally mediate replication fork stability, including members of the Fanconi anemia gene family and the helicases PIF1 and RECQL5, showed reduced accumulation at replication forks in the absence of RNF4." (PMID 38530355, 2024).
leukemia (3 papers, 2013 to 2021). A malignant (clonal) hematologic disorder, involving hematopoietic stem cells and characterized by the presence of primitive or atypical myeloid or lymphoid cells in the bone marrow and the blood. "In a recent in vitro investigation, we found that RSV-induced NRF2 degradation occurs in a RING finger protein 4 (RNF4)–promyelocytic leukemia (PML)-dependent manner." (PMID 35052571, 2021). "In particular, the RING finger protein 4 (RNF4) described initially in promyelocytic leukemia cells (PML), has been shown to target a variety of SUMO2/3 conjugates for proteasomal degradation." (PMID 29371964, 2017). "Like RNF4, the prototypic cellular STUbL, K-Rta degrades SUMO-2/3 and SUMO-2/3 modified proteins, including promyelocytic leukemia (PML) and K-bZIP." (PMID 23990779, 2013).
lymphoma (3 papers, 2022 to 2024). A malignant (clonal) proliferation of B- lymphocytes or T- lymphocytes which involves the lymph nodes, bone marrow and/or extranodal sites. "We find that the block on cell growth caused by conditional inactivation of Rnf4 is so strong as to limit the outgrowth of c-myc–dependent lymphomas." (PMID 38530355, 2024). "PARPi sensitivity of SENP6-deficient lymphoma cells was shown to be predominantly, but not completely RNF4-dependent, suggesting that RNF4-independent regulation of some DDR proteins by SENP6 is also important for maintaining genomic integrity." (PMID 37735495, 2023). "Given the abundant expression of Rnf4 in MYC-driven lymphomas, we hypothesized that co-depletion of RNF4 and SENP6 may impair PARPi sensitivity." (PMID 35022408, 2022).
colorectal cancer (2 papers, 2013 to 2025). A primary or metastatic malignant neoplasm that affects the colon or rectum. "Since RNF4 plays a unique role in ubiquitylation, DNA demethylation, and DNA repair, the colorectal cancer progression may involve the abnormal ubiquitylation and demethylation." (PMID 23586028, 2013). "RNF4-mediated ubiquitination of PDHA1 has been demonstrated to play a critical role in promoting glycolytic metabolism, proliferation, and metastasis in colorectal cancer, and PDHA1 overexpression has been shown to inhibit CRC cell proliferation, migration, and invasion." (PMID 41050056, 2025).
Ewing sarcoma (2 papers, 2021 to 2022). A small round cell tumor that lacks morphologic, immunohistochemical, and electron microscopic evidence of neuroectodermal differentiation. "Importantly, patient-derived sarcomas such as osteosarcoma, Ewing sarcoma, liposarcomas, and leiomyosarcomas exhibit high levels of RNF4 and BMP6, which are associated with reduced patient survival." (PMID 36153321, 2022). "Our analysis identified TRIM25, APP, ELAV1, RNF4, and HNRNPL as ideal mRNA targets for Ewing sarcoma therapy." (PMID 34662337, 2021).
lung adenocarcinoma (2 papers, 2016 to 2024). A carcinoma that arises from the lung and is characterized by the presence of malignant glandular epithelial cells. "In human lung adenocarcinomas cells, RNF4 targeted NDRG2 to proteasomal degradation by stimulating its SUMOylation." (PMID 27072586, 2016). "Endogenous RNF4 expression was increased in human lung adenocarcinomas cells, and there was a concomitant upregulation of SUMO." (PMID 27072586, 2016). "Elevated RNF4 expression is a feature of several tumor types in The Cancer Genome Atlas (TCGA) data sets, and high RNF4 expression correlates with poor survival in multiple tumor types, including breast adenocarcinoma and lung adenocarcinoma." (PMID 38530355, 2024).
myocardial infarction (2 papers, 2020 to 2024). Gross necrosis of the myocardium, as a result of interruption of the blood supply to the area, as in coronary thrombosis. "The knockout of a poly-SUMO-specific E3 ubiquitin ligase RNF4 has been shown to aggravate interstitial fibrosis and cardiac dysfunction in the animal model of myocardial infarction." (PMID 39697538, 2024). "Here, we examined RNF4 expression following myocardial infarction (MI) or H2O2/arsenic trioxide (ATO) treatment in vitro and in vivo." (PMID 32722882, 2020). "Treatment with arsenic trioxide, which is an ROS inhibitor, reduces RNF4 expression and PML SUMOylation to suppress myocardial apoptosis and fibrosis against myocardial infarction." (PMID 39697538, 2024). "Upon myocardial infarction (MI) or H2O2/ATO treatment, RNF4 increased rapidly and then decreased gradually." (PMID 32722882, 2020).